PIK3CA (phosphatidylinositol-4,5-bisphosphate 3-kinase catalytic subunit alpha)
Diseases named in the same sentence as PIK3CA in open-access papers (continued):
Sharing a sentence is not in itself a finding about the gene and the disease.
cancer (continued). "Taselisib is being tested in a phase II study in patients with different cancers (excluding breast) with PIK3CA mutation but without KRAS mutation or PTEN loss." (PMID 33801659, 2021). "The co-occurrence of MET and KRAS or MET and PIK3CA might increase the aggressiveness of cancer cells, including cell proliferation, survival, invasion, or metastasis." (PMID 34439385, 2021). "PIK3CA is a well-known oncogene that can play an important role in cancer development." (PMID 34194478, 2021). "Hence, the PIK3CA mutation test helps to discriminate between tumors, which are indeed supported by PI3K activation, and cancers that are characterized by the involvement of other signaling pathways." (PMID 34681592, 2021). "PIK3CA is involved in cell growth, proliferation, and cell death inhibition, leading to cancer." (PMID 35053185, 2021). "As MCF-7 cells have a mutation in the PIK3CA gene, we explored if activity of compounds that target the PI3K pathway is affected by alterations of this gene by exploring the Genomics of Drug Sensitivity in Cancer database." (PMID 34944934, 2021). "Furthermore, the cancer cell lines differ in KRAS, BRAF and PIK3CA mutations, which are known to directly affect metabolic reprograming through their involvement in the MAPK/ERK signaling pathway." (PMID 33671096, 2021). "PIK3CA variants were more frequent but not restricted to HR-positive cancers and were mostly observed in premenopausal patients." (PMID 34504096, 2021). "Moreover, we also conducted cancer pathway activity and drug sensitivity analysis of hub genes (PIK3CA, STRN, C9orf102, REST, and NHLRC2) obtained from LinkedOmics." (PMID 34367282, 2021). "Early preclinical studies with the PI3K inhibitors Wortmannin and LY294002 suggested that the complete inhibition of all PI3K isoforms could provide a positive response to treatments in PIK3CA-mutant cancers." (PMID 33809714, 2021). "As heterozygosity for PIK3CA c.3140A>G is considered lethal, relatives do most probably not have an increased risk for cancer." (PMID 34075207, 2021). "In conclusion, our study suggests that vitamin C expands the therapeutic window of PI3K inhibitor buparlisib in treating PIK3CA-mutated TNBC by promoting KDM5-mediated H3K4 demethylation to suppress the expression of PI3K pathway genes and other genes relevant to cancer growth and metastasis." (PMID 33664847, 2021). "In addition, dysregulation of PIK3CA is also a usual event during cancer progression, and it is regulated by multiple miRNAs." (PMID 33509213, 2021). "Activating mutations and amplification in PIK3CA, the gene encoding the p110α catalytic subunit of PI3K have been reported to frequently mutated in different types of human cancer such as prostate (29%), breast (27%), endometrium (23%), colon (15%), upper aerodigestive tract, etc (10%)." (PMID 35250965, 2021). "With links to mTOR, Akt and cMyc, it comes as no surprise that PIK3CA mutations can influence metabolic programs in a number of cancer types." (PMID 34283054, 2021). "In many cancers, mutation of ARID1A has been found to co-occur with mutations in the PI3K/AKT pathway, among which the coexistence of ARID1A deficiency and phosphatidylinositol 3-hydroxy kinase (PIK3CA) mutation is a more typical phenomena." (PMID 34671561, 2021).
cancer (continued). "Altogether, high levels of phosphorylated Akt signify AKT dependency in PIK3CA-mutant cancer cells." (PMID 33916378, 2021). "In this study, we show that in the context of PIK3CA mutation or amplification, high expression of fascin actin-bundling protein 1 (FSCN1) (using the median as the cut-off value) is associated with poor prognosis and radiotherapy response in cancer patients." (PMID 34249689, 2021). "PIK3CA, a member of the phosphatidylinositol 3’-kinase (PI3K) family, is ranked as the second most commonly mutated oncogene, detected in more than 10% of patients with eight types of cancer." (PMID 35004676, 2021). "In addition to these overlapping histopathologic changes, we further note that these carcinomas from both sites show consistent CYLD mutations, HPV positivity, low TMB, low frequency of PIK3CA mutations, and likely propensity to metastasize to the liver." (PMID 32892208, 2021). "It has been observed that PROS not involving the brain are usually caused by PIK3CA cancer hot-spot variants, e.g. p.Glu542Lys, p.His1047Arg and p.Glu453Lys, while PROS involving the brain are usually caused by relatively rare variants." (PMID 33054853, 2020). "Our prediction model is not an application that is immediately applicable to a cancer patient for detection of PIK3CA mutation." (PMID 33166334, 2020). "However, these CRC cells also contain mutations in other cancer related genes (HCT116: KRAS, PIK3CA, CTNNB1, BRCA2, CDKN2A etc.; SW480 or SW620: KRAS and APC etc.), which constitute a unique pathological context in every CRC cell." (PMID 32388500, 2020). "Our results suggest that, like in cancer, optimal therapeutic benefit may require targeting both the endothelial cell-autonomous PIK3CA-driven signaling and the microenvironment-derived paracrine signaling that contribute to driving pathological vessel growth." (PMID 32513927, 2020). "It is associated with PIK3CA H1047R mutations, which are implicated in multiple cancers; yet, this condition is not known to associate with cancer, although further longitudinal studies are necessary." (PMID 32066498, 2020). "Accordingly, mechanisms that overactivate the PI3K/AKT axis or impair its inactivation (such as mutations in PIK3CA and/or PTEN genes, for example) range amongst the most prominent molecular aberrations in cancer and resemble mutational hot spots for resistance development." (PMID 31477842, 2020). "Mutant PIK3CA promotes cell growth and invasion of human cancer cells." (PMID 33375317, 2020). "The PI3KCA gene encodes PIK3CA of class IA PI3K and PI3KCA gene mutations and amplifications cause increased enzymatic activity of PIK3CA, activation of AKT signaling, and growth factor-independent growth, invasion, and metastasis of cancer cells." (PMID 32012988, 2020). "PIK3CA oncogenic alteration in many cancers derived the hypothesis of its role in the development of PC." (PMID 33247697, 2020).
cancer (continued). "Importantly, in human cancers, PIK3CA/PTEN mutants and NRAS mutants provide two distinct therapeutic targets suitable for pharmacological intervention." (PMID 32210430, 2020). "Notably, all three YAP1/WWTR1 compensable cell lines (BICR10, HSC-2 and HSC-4) harbor PIK3CA mutation, and that alterations in the PI3K signaling pathway have been linked to multiple metabolic dysregulations in cancer." (PMID 32990596, 2020). "We also observed significantly more mutations of PIK3CA [frequently found in microsatellite unstable (MSI) GCs] and ARID1A (associated with MSI along with hypermutations and PD-L1 expression in cancers including GC) in the INT subtype compared to the COD subtype." (PMID 31773340, 2020). "Finally, ARQ 751 is currently being tested in a phase 1 study for solid tumours with PIK3CA/AKT/PTEN mutations (NCT02761694) both as monotherapy and in combination with other anti-cancer agents." (PMID 32453400, 2020). "Mutant PIK3CA is known to promote the proliferation and invasion of human cancer cells." (PMID 32704014, 2020). "A large-scale survey of cancer genomic and therapeutic databases has identified five candidate genes, namely PIK3CA, BRAF, NF1, NRAS, and PTEN, the targeting of which could be suitable for combination therapy with immunotherapy." (PMID 32483262, 2020). "Multiple platforms, which examined the relationship between PIK3CA mutation and protein expression, have demonstrated that pAKT and pS6 were not elevated in PIK3CA-mutated luminal cancers; instead, they were highly expressed in basal-like and HER2 subtypes." (PMID 30729154, 2019). "In particular, APOBEC activity is responsible for the generation of PIK3CA gene mutation across multiple cancers, which may explain the positive association between HPV integration and PIK3CA mutation in our series." (PMID 31766658, 2019). "Notably, activating mutations in the catalytic domain of PI3K, i.e., PIK3CA, and loss-of-function mutations in PTEN are among the most common genetic alterations found in human cancer, demonstrating the central role of this phosphoinositide in cancer biology." (PMID 32039198, 2019). "This unique genetic representation indicates that the combination of PIK3CA/PTEN alterations might play an important synergistic role in tumorigenesis of these cancers." (PMID 31289610, 2019). "Additionally, these results demonstrate that in vivo therapeutic benefit for the combination of MEK and TNKS inhibition in KRAS and PIK3CA mt cancers." (PMID 30944457, 2019). "While the majority of mouse models of PIK3CA mutation have focused on tumorigenesis, these models also allow for the study of other pathogenic effects of PIK3CA mutation that are not related to cancer." (PMID 31018529, 2019). "Whether mTORC1 activation and/or RB phosphorylation take place dynamically in treatment-naïve PIK3CA-mutant cancer cells following p110α inhibition is unclear and requires further study." (PMID 35582276, 2019). "These genes have been linked to various cancers, yet their presence in PIK3CA (H1047R) cells is not sufficient to induce anchorage-independent growth." (PMID 31652979, 2019). "Targeting PIK3CA to investigate and develop drugs may be a new way for better treatment of cancer, including UCEC." (PMID 31472672, 2019).
cancer (continued). "However, PIK3CA and PTEN showed more frequent mutation rates in pan-cancer cell lines and tumors and were very consistent with the previous reports suggesting that more proven contribution of this pathway gene in the pathogenesis of solid pan-tumors." (PMID 31289610, 2019). "On the other hand, the frequency of SMAD4 and PIK3CA mutation was higher in patients without germline cancer-associated variants (17% and 15%, respectively) than those with variants (8% and 8%, respectively)." (PMID 30850667, 2019). "PIK3CA mutations are mainly found in EBV-positive GC, and it is one of the driver genes in cancer." (PMID 31781598, 2019). "Thus, TCI detected the shared functional impact of distinct types of SGAs perturbing PIK3CA across different cancer types." (PMID 31276486, 2019). "The p110a (PIK3CA), a catalytic subunit of PIK3, is mutated in many types of cancers." (PMID 32099598, 2019). "Also, there were increases in PIK3CA mutations, AKT copy numbers, and phosphorylation of PI3K/AKT pathway components in metaplastic carcinomas compared to most other breast tumor subtypes." (PMID 31881983, 2019). "As in cancer, PIK3CA mutations in PROS arise postzygotically, but unlike in cancer, these mutations arise during embryonic development, with their timing and location critically influencing the resulting disease phenotype." (PMID 30197175, 2018). "PIK3CA E545K ranked among top 5 in 5 cancer types, but very low in KIRC and GBM." (PMID 29738578, 2018). "In summary, we identified differential expression and phosphorylation of AKT1 and AKT2 isoforms in different cancer lineages and genetic backgrounds, including the selective activation by PIK3CA hotspot mutation H1047R of AKT2 but not AKT1." (PMID 30012111, 2018). "Enrichment of PIK3CA mutations in HPV(+) HNSCC was first noted in WES studies, which was later confirmed by another targeted sequencing study of 51 cases of mostly advanced HPV(+) HNSCC (617 cancer-associated genes)." (PMID 29933636, 2018). "The response to treatment according to the Residual Cancer Burden (RCB) score was not significantly related to the PIK3CA mutational status, as the frequency of PIK3CA mutations was similar in patients with pCR, RCB-I, RCB-II or RCB-III (p 0.454)." (PMID 29937992, 2018). "Somatic activating mutations in the PIK3CA gene were found in more than 10% of high-grade serous and 40% of clear cell ovarian carcinomas, and constitutive activation of the PI3K/Akt/mTOR axis is known to confer drug resistance to many types of cancer." (PMID 29930760, 2018). "PIK3CB (the gene encoding p110β) promotes cancer cell proliferation and tumorigenesis in the absence of mutations, especially in wild-type PIK3CA and PTEN-deficient cancers." (PMID 29596304, 2018). "PIK3CA mutations were found in 5 (25%) of the 20 ASCC, corresponding to the classical somatic activating hot-spot mutations described in the COSMIC database of somatic mutations in cancer." (PMID 29416628, 2018).
cancer (continued). "This assay could be used to distinguish between a mutant type and wild‐type, and thus, three recurrent oncogenic point mutations in genes KRAS, PIK3CA and IDH1 in human cancer cell lines have been identified." (PMID 30338908, 2018). "In a separate study, uterine lavage fluid, which contains mostly endometrial cells, showed abundant cancer driver mutations mostly in PIK3CA, KRAS, and PTEN both in women with and without endometrial cancer." (PMID 29300727, 2018). "Overall, PIK3CA mutations have been associated with KRAS mutant, MGMT methylated, and CIMP cancers; however, PIK3CA mutations in the catalytic exon 20 hotspot were found predominantly in BRAF mutant/MSI cancers." (PMID 30598662, 2018). "As our erlotinib-treated PIK3CA-comutated case, these data suggest that PIK3CA-mutations despite being considered cancer-drivers do not necessarily represent a mechanism of primary resistance to erlotinib in EGFR-mutated NSCLC." (PMID 29899852, 2018). "PIK3CA-mutant cancers are also an ongoing challenge to treat clinically; co-occurring drugs targeting the PI3K pathway have been more effective than single-agent PI3K inhibition in treating PIK3CA-mutant cancers, but efficacy varies with mutation profile." (PMID 30053901, 2018). "Intriguingly, de novo germline and postzygotic, somatic mosaic mutations in similar locations in PIK3CA and PIK3R2 (p85β) also lead to overgrowth and developmental disorder syndromes, revealing that the same mutant can lead to cancer and/or developmental disorders." (PMID 29616047, 2018). "Tissues are not uniformly affected, and, surprisingly, no excess of PIK3CA-associated adult cancers has been described." (PMID 30197175, 2018). "Interestingly, in these cancers, alterations of gene encoding for components of the BAF complex frequently co-occur with activating mutations in PIK3CA." (PMID 30333046, 2018). "Combination of Pten deletion and Pik3ca mutation leads to carcinoma, while Pik3ca mutation alone showed no EMC or hyperplasia phenotype." (PMID 30142194, 2018). "PIK3CA is a potential therapeutic target for various carcinoma treatments." (PMID 29970892, 2018). "As a translational application case, we demonstrate enhanced reproducibility of genetic interaction partners of common cancer drivers, as well as identify novel synthetic lethal partners of a major oncogenic driver, PIK3CA, supported by a complementary CRISPR/Cas9 experiment." (PMID 28569207, 2017). "The phosphoinositide 3-kinase (PI3K)–Akt–mammalian target of rapamycin (mTOR) pathway plays a pivotal role in cancer cell proliferation, and mutations in the PIK3CA gene are commonly found in various cancers regardless of histological subtypes." (PMID 28068934, 2017). "Akt is frequently abnormally activated in cancers due to aberrant activity of upstream receptors, activating mutations in the catalytic subunit of PI3K (p110 alpha, PIK3CA) or inactivating mutations in the phosphatase and tensin homolog (PTEN) lipid and protein phosphatase." (PMID 27999207, 2017). "The implications of synchronous presence of aberrantly active MET and PIK3CA mutations in cancer has not been previously explored." (PMID 28532501, 2017).